CD4 (CD4 molecule)
Diseases named in the same sentence as CD4 in open-access papers (continued):
Sharing a sentence is not in itself a finding about the gene and the disease.
melanoma (continued). "TRP-1 CD4+ T cells can eradicate B16 melanomas through direct recognition and cytolytic destruction." (PMID 37316667, 2023). "A lower percentage of CD25+ cells within the CD4+ T cell compartment was detected in melanomas of Colec11–/– mice compared with WT mice." (PMID 36883567, 2023). "A very recent study on B16 melanoma metastasis showed that IL9 from CD4+ T cells exerted protumor functions by inducing the expression of Arg1, an M2 marker, in pulmonary interstitial macrophages." (PMID 36968220, 2023). "In this study, we found that the infiltration of fewer immune cells in melanoma-beared RNF8 deficient host compared with the control host, including CD4+ T, CD8+ T, and NK cells." (PMID 37391451, 2023). "T cell immunoglobulin and mucin-domain containing-3 (TIM-3) found in melanoma-derived exosomes suppressed the immune function of CD4+ T cells and induced the M2 polarization of macrophages." (PMID 36674479, 2023). "The activation of caspase 3, 7 and 9 in CD4 + T cells downregulated the anti-apoptotic proteins and resulted in faster melanoma cell growth in mice." (PMID 37022605, 2023). "Our results showed that high expression of ITGAL was significantly positively correlated with CD4+ T cells and CD4+ T cells in melanoma." (PMID 37388230, 2023). "Experiments in mice with melanoma have shown that depleting total B cells impaired CD4+ and CD8+ effector memory T cell proliferation following tumour antigen exposure, doubling tumour volume and metastasis." (PMID 37324393, 2023). "Circulating CD4+CD26high T cells were significantly reduced in melanoma patients compared to healthy subjects (p = 0.001)." (PMID 37170241, 2023). "In a melanoma tumor model, the adoptive transfer of tumor antigen‐specific CD4+ T cells can prevent tumor progression." (PMID 37829505, 2023). "Increased expression of CENPF results in early exhaustion and immune suppression of CD4 + T cells, suggesting its potential as a predictive indicator for melanoma spread and a target for treatment." (PMID 38097686, 2023). "PD-L1 binding to PD-1 suppresses the immune response through CD8+ T cell inhibition and CD4+T-regulatory lymphocyte activation, and melanoma tumor cells use this mechanism." (PMID 36836455, 2023). "In that regard, MV3 melanoma cells deliver TIM-3 to CD4 + T cells via exosomes to inhibit their function." (PMID 37022605, 2023). "While some cancers do not express MHC class II molecules and thus cannot be directly recognized by CD4 T cells, human melanoma, MCC, and murine B16F10 cells can express MHC class II molecules, with upregulated expression observed in the presence of IFNγ." (PMID 37711623, 2023). "Treatment with guadecitabine/ICBs down modulated the percentages of CD4+ Tregs in the SC model of melanoma." (PMID 36934257, 2023). "Taken together, these data support the notion that Activin-A in melanoma diminishes intratumoral CD8+ compared to CD4+ T cells, and despite increased IFN signaling across the TME." (PMID 38304252, 2023). "According to the results of single-cell sequencing, melanoma cell subsets can be divided into 8 types, namely B cells, CD4+ T cells, CD8+ T cells, dendritic cells, fibroblasts, monocytes/macrophages, plasma cells, proliferating T cells." (PMID 37666853, 2023). "High S100A9 levels in peripheral blood monocytes and a lower ratio of CD4+ T cells/monocyte was previously found to correlate positively with poor response to anti-PD-1 immunotherapy but inversely with overall survival in melanoma patients." (PMID 37347110, 2023). "Another study demonstrated that the TME of BRAF‐mutant melanoma is associated with decreased CD8+ T‐cells and increased B‐cells and CD4+ T‐cells, which is distinct from BRAF wild‐type." (PMID 37584204, 2023). "Taken together, the study by Oliveira and colleagues unveils the in-depth characterization of treatment-naive melanomas, disclosing the relationship between tumor-specific CD4+ TILs and tumor cells." (PMID 36646683, 2023).
melanoma (continued). "Increasing studies have shown that CD4 + T cells is critical for productive anti-tumor responses through recognition of antigens in melanoma." (PMID 37950289, 2023). "have identified three general types of potential interactions between tumor-specific CD4+ tumor-infiltrating lymphocytes (TILs) cells and melanoma in a cohort of CM." (PMID 38299143, 2023). "We assessed potential associations between tumor fucosylation, total/fucosylated HLA-DRB1, CD4+ T cells and responder status in expanded cohorts of patients with melanoma treated with anti-PD1 therapy." (PMID 36690875, 2023). "After ipilimumab (anti-CTLA-4) treatment, patients with melanoma had an increased absolute lymphocyte count (ALC) and delayed enhancement of CD4+ and CD8+ T cells, which was associated with a positive outcome." (PMID 38328405, 2023). "For instance, one study demonstrated that immunization of mice with citrullinated peptides derived from alpha enolase led to increased survival rates and a strong CD4+ T-cell response in tumour models of melanoma, pancreatic carcinoma and lung carcinoma." (PMID 37778382, 2023). "Here, we show that oBHV is sufficient to induce bona fide ICD within immune cold melanoma tumors, resulting in the influx of CD4+ and CD8+ TILs." (PMID 36831636, 2023). "CD4+ T cells were shown crucial for mediating anti-melanoma effects, and their depletion resulted in substantial diminution of antitumor effects of the vaccination with HCA587 protein." (PMID 36674479, 2023). "NLRC4 activation is critical for cytokine and chemokine production in tumor-associated macrophages and is required to generate CD4+ and CD8+ T cells in the B16F10 melanoma mouse model." (PMID 37864090, 2023). "Similar results have been detected on T cell subsets in other types of cancer, such as BTLA upregulation on peripheral CD4 + T cells in hepatocellular carcinoma or tumor antigen-specific CD8 + T cells from melanoma." (PMID 37041226, 2023). "In melanoma, LMD is associated with a suppressive immune microenvironment characterized by a high number of apoptotic and exhausted CD4+ T-cells, myeloid-derived suppressor cells, and a low number of CD8+ T-cells." (PMID 36980770, 2023). "Another important immune regulatory cell in melanoma and other cancers is Treg cells (CD4+CD25+ regulatory T cells), which have an immunosuppressive function by increased expression of CTLA-4 and PD-1, resulting in suppression of antitumor immunity." (PMID 37037839, 2023). "Despite their relatively poor in vivo expansion, adoptively transferred TRP-1 CD4+ T cells eradicated established B16 melanomas as efficiently as Pmel-1 CD8+ T cells." (PMID 37316667, 2023). "Recent studies of human bladder cancer and melanoma identified genetic signatures corresponding to cytotoxic CD4+ T cells among TILs." (PMID 36512410, 2023). "Several recent studies have reported that a higher frequency of circulating central memory T cells (CD4 and CD8) is associated with an increased tumor inflammatory profile in melanoma patients and with longer survival times." (PMID 37170241, 2023). "In conclusion, fucosylation of HLA-DRB1 is a key regulator of itIC abundance in melanomas, and this mechanism, together with fucosylation-regulated CD4+ T cell biology, can be therapeutically exploited using oral l-fuc administration." (PMID 36690875, 2023). "Overall, in comparison to healthy controls, melanoma patients demonstrated reduced numbers of CD4 and CD8 naive T cells coupled with indications of memory T‐cell activation denoted by increased Ki67 and IL‐2 positivity and a skewed γδT‐cell phenotype." (PMID 37692904, 2023). "Flow cytometric analysis of TILs confirmed that at least 20% of metastatic melanomas accommodate CD4+ anti-tumor effector cells with specific tumor recognition." (PMID 38328405, 2023). "In cutaneous melanoma, high infiltration of CD4 memory-activated T cells promotes melanoma metastasis." (PMID 37362244, 2023).
melanoma (continued). "In melanoma, CD4+ PD-1- CD127low T cells subset, suggesting unexhausted cells, increased in responders treated with ICI compared to non-responders." (PMID 35008422, 2022). "Based on the pivotal role of T cells in curbing melanoma metastatic foci growth in the lungs, we assessed the infiltration of CD4+ and CD8+ T cells in the lungs on day 14 following the tail vein injection of WT and B2m-/- B16 melanoma." (PMID 36733396, 2022). "To directly assess the importance of T cells in Ruxo therapy, we treated IFNγR1KO melanoma-bearing mice with anti-CD4 and anti-CD8 neutralizing antibodies prior to and during Ruxo therapy." (PMID 36008408, 2022). "The 856 CD4+ T cells identified by the authors from 33 human melanoma tumors were extracted and analyzed with Seurat pipeline." (PMID 36107619, 2022). "Although NK cells from the melanoma-bearing lungs are largely excluded from the established B16 metastatic foci, they promote the recruitment and infiltration of CD4+ and CD8+ T cells into the metastatic foci in the lungs." (PMID 36733396, 2022). "The pretreatment TCR repertoire of CD4-positive T cells in melanoma patients is significantly more restricted than that in healthy individuals." (PMID 36361781, 2022). "Of note, among IVneg immune effector populations in the lungs, T cells, especially CD4+ T cells, showed the most robust increase in response to WT and B2m-/- B16 melanoma challenge compared to the untreated control mice." (PMID 36733396, 2022). "In a murine melanoma model, adoptive cell therapy with CD4 and CD8 T cells results in enhanced tumor regression compared to adoptive transfer of CD8 T cells alone." (PMID 35565329, 2022). "Melanoma arising in five patients on this trial had significant increases in CD4+ and CD8 T cells in peritumoral and tumor infiltrating sites compared to five melanoma in the placebo group." (PMID 35053490, 2022). "Infection of human melanoma cells by NDV was reported to provide co-stimulatory activity towards autologous melanoma-specific CD4+ T helper cell TILs." (PMID 36361831, 2022). "Along with Ag presentation by HLA class II molecules on the surface of melanoma cell lines, the costimulatory signals received by T cells play a key role in enhancing and prolonging the activation of CD4+ T cells." (PMID 35162988, 2022). "CD25-Foxp3+CD4 Tregs significantly increased in melanoma TILs and decreased in dLNs after treatment with anti-PD-1 but not anti-CD80 mAbs, implying PD-1 blockade prevented CD25−Foxp3+CD4 egress from tumor to dLNs." (PMID 35449134, 2022). "Taking advantage of our scRNA-seq analysis, we illustrated strong interactions of melanoma cells having “Immune cell interactions” GES with CD4+ and CD8+ T cells." (PMID 35884783, 2022). "Previous studies have also shown a melanoma mouse model with CD4 + T cell depletion developed hair coat depigmentation." (PMID 36182982, 2022). "Heterogeneous expression of melanoma differentiation antigens and immune infiltrates (CD4+ and CD8+ IHC staining) was observed in 11 melanoma samples." (PMID 35740696, 2022). "An increase in cathepsin D expression and activity would aid melanoma cells in enhanced Ag processing and the presentation of class II–peptide complexes to CD4+ T cells." (PMID 35162988, 2022). "In murine melanoma and colon adenocarcinoma models, both CD4 and CD8 T cells are necessary for response to anti-PD-1 treatment." (PMID 35565329, 2022). "An in-depth analysis of CD4+ T cells infiltrating human melanoma specimens revealed the diverse targets of anti-tumor CD4+ TCRs, including MHC class II-restricted neoantigens and HLA class I-restricted TAAs." (PMID 35928827, 2022). "In melanoma, a high level of potassium was released from the necrotic tumor cell, which inhibits CD4+ and CD8+ T-cell activities, resulting in the blockade of antitumor immunity." (PMID 35957699, 2022).
melanoma (continued). "To find out, we analyzed the TCRβ repertoires of memory and naïve CD4 T cells in a small cohort of four gender- and age-matched elderly patients having the autoimmune blistering disease bullous pemphigoid or non-melanoma skin cancers." (PMID 36458004, 2022). "On the other hand, immunomodulatory therapy in melanoma is currently an important tumor therapy method, e.g., anti-CD4 and anti-PD-L1 therapy, which are used for clinical validation." (PMID 35893303, 2022). "In the current study, we report that increased GILT expression generates a greater pool of antigenic peptides in melanoma cells for enhanced CD4+ T cell recognition." (PMID 35162988, 2022). "CD73+CD4+CD25high Tregs exhibit immunosuppressive effects, which pave the way for melanoma cells to escape nivolumab, pembrolizumab, and tislelizumab treatment." (PMID 36359776, 2022). "Conversely, a negative correlation between OPN4 levels and the abundance of several immune cells, such as B and CD4+ lymphocytes, and M1 macrophages was found; a positive correlation was found for mast cells and neutrophils in human melanoma." (PMID 35562405, 2022). "Our results showed a significant increase of cell percentage of monocytes (CD11b+Ly6C+) and neutrophils (CD11b+Ly6G+) in lung of melanoma mice, while a reduced percentage of CD4+ and CD8+ T cells." (PMID 36132145, 2022). "Another study using TCR-tg mice and ACT of tumor-specific CD4+ T cells demonstrated that mouse lymphoma and melanoma were rejected through an IFNγ-dependent mechanism that involved indirect activation of CD4+ T cells by secreted antigen expressed on host APCs." (PMID 36159781, 2022). "Consistently, it has been shown that the immune effect of GM on melanoma is enhanced by promoting the reaction of CD4+ T and CD8+ T lymphocytes." (PMID 35875081, 2022). "Clinical data revealed a significant link between low frequencies of circulating CD73+CD8+ T lymphocytes and CD73+CD4+ regulatory T cells and better general survival of melanoma patients." (PMID 36428970, 2022). "The reduction of NRF2 can significantly induce CD8+ and CD4+ T cells to infiltrate tumors and inhibit the melanoma progression." (PMID 36439878, 2022). "We have previously identified 6 antigenic peptides derived from melanomas that have proven efficacious for activating CD4+ T cells in clinical trials for melanoma." (PMID 36176766, 2022). "CD4+ T cells that express NK cell markers and cytotoxic enzymes have also been reported in human bladder cancer, NSCLC, melanoma, and hepatocellular carcinoma, and these CD4+ NK-like T cells have been shown to have tumor killing activity." (PMID 36382146, 2022). "In contrast, PD1 expression on IVneg CD4+ T cells from the lungs was significantly elevated in WT and B2m-/- B16 melanoma-challenged mice (“CD4”)." (PMID 36733396, 2022). "Cutaneous melanomas showing regression revealed lower counts of CD4-positive Treg cells and PD-1-expressing exhausted T cells." (PMID 35463364, 2022). "For instance, CD244 can mediate immune escape in mice with melanoma by regulating CD4+ and CD8+ T-cell expression." (PMID 36213111, 2022). "RBM38 CNV was found to be strongly related to immune infiltration in malignant melanoma, containing CD4+ T cells, CD8+ T cells, B cells, neutrophils, macrophages, and dendritic cells." (PMID 35326741, 2022). "In the group of melanoma-CM-educated moDCs, TNFα secretion negatively correlated with the ability of moDCs to induce IL-10 producing CD4+CD25+ T cells." (PMID 36194602, 2022). "Ipilimumab is a monoclonal antibody (mAb) targeting cytotoxic T-lymphocyte associated protein (CTLA-4), demonstrating increased lymphocyte counts and CD4+/CD8+ T cell percentages in melanoma patients correlated to improved survival." (PMID 35345849, 2022).
melanoma (continued). "Another study of 4 patients with advanced melanoma found that ipilimumab generated or augmented multiple T helper type 1 (Th1) dominant CD4+ T cell responses, seen by analysis of in vitro cultured CD4+ T cells isolated from patients’ peripheral blood." (PMID 36159781, 2022). "CD4+/CD8+ T-cell ratio was significantly predictive of PFS benefit with sparta-DabTram but requires further validation as a biomarker in melanoma." (PMID 35728875, 2022). "In contrast, in invasive primary melanoma biopsies, we observed many more CD4+ cells, among which we identified GATA3+FOXP3– cells, GATA3–FOXP3+ cells, and GATA3+FOXP3+ cells." (PMID 36107619, 2022). "While cytotoxic CD8+ T cells are able to destroy melanoma cells, their interaction with tumor cells and killing efficiency are greatly supported by CD4+ helper T cells, which produce inflammatory cytokines and chemokines to accelerate host immunity." (PMID 35162988, 2022). "Previous study revealed that IL-9-producing CD4+ T cells, a type of T helper cells, had potent abilities in eradicating melanoma." (PMID 35171924, 2022). "Accordingly, pSTAT3 expression on peripheral-blood CD4+ T cells and Tregs from melanoma patients was correlated with the clinical benefit from adjuvant treatment with PD-1 inhibitor." (PMID 35205801, 2022). "A higher percentage of OX40+ cells within FOXP3+CD4+ Tregs was observed in invasive melanoma compared with in situ melanoma, suggesting an enrichment of OX40+ Tregs in invasive melanoma." (PMID 36107619, 2022). "Analysis of functional Ag presentation by the melanoma cell lines revealed that GILT expression enhanced CD4+ T cell recognition of antigenic epitopes displayed in the context of HLA class II proteins on tumor cells." (PMID 35162988, 2022). "The strategy consists of brief inoculation of B16F10 melanoma cells and CD4 + regulatory T cell depletion." (PMID 36182982, 2022). "We found that PD1+ IVpos CD4+ T cells remained comparable between the control and WT and B2m-/- B16 melanoma-challenged mice (“CD4”)." (PMID 36733396, 2022). "Using flow cytometry analyses, we observed that the CTLA-4 mAb led to a marked reduction in CD4+CD25+FoxP3+ Tregs in melanoma, consistent with early studies." (PMID 36050478, 2022). "The optimized vaccine has the unique ability to amplify tumor-specific CD4+ T cells, which improves antitumor sensitivity, and has a significant effect on the prevention and therapy of melanoma mice." (PMID 35748951, 2022). "Melanoma growth and progression have been correlated with the presence of CD4+CD25+ regulatory T cells (Treg)." (PMID 35248056, 2022). "IL-12 inhibits melanoma progression via increasing the infiltration of NK cells and CD8α+ T cells, and a decreased presence of CD4+Foxp3+ regulatory T cells." (PMID 36428682, 2022). "Blockage of PGE2 production by SC completely abrogated upregulation of CD73 and PD-1 expression on CD8+ and CD4+ T cells induced by melanoma-treated SC to the control levels." (PMID 36428970, 2022). "In this study, we found that B. microti infection can effectively inhibit the growth of melanoma cells and prolong the survival time of tumor-bearing mice by stimulating the immune system, especially increasing the number of CD4+ T cells and macrophages." (PMID 35814662, 2022). "In melanoma patients, increased TIGIT/CD226 ratio was observed in CD4+ Tregs compared with CD4+ effector T cells and was associated with highly suppressive TME and poor clinical outcomes." (PMID 35656508, 2022). "Another study of 32 advanced melanoma biopsies identified a cytotoxic subset within the CD4+ T cell population in different patients and described its genetic signature." (PMID 36159781, 2022). "Increased levels of IL-8 and IL-10 in melanoma, circulating effector memory CD4+ and intratumoral CD8+ T cells in both tumor types were detected after therapy." (PMID 34777395, 2021).